HMGA2 (high mobility group AT-hook 2)
Diseases named in the same sentence as HMGA2 in open-access papers (continued):
Sharing a sentence is not in itself a finding about the gene and the disease.
pancreatic cancer (62 papers, 2003 to 2026). "A more advanced tumor stage was associated with higher HMGA2 levels according to immunohistochemical (IHC) staining of a total of 63 PAAD samples from the pancreatic cancer tissue chip." (PMID 38493165, 2024). "To investigate the impact of Hmga2 deficiency on pancreatic cancer phenotypes in KP172CT and KPHetCT mice, we assessed tumour histology." (PMID 30228296, 2018). "HMGA2 has been previously implicated in resistance to gemcitabine in human pancreatic cancer cell lines in vitro, where HMGA2 knockdown sensitized PDAC cells to gemcitabine treatment." (PMID 30228296, 2018). "Further validation showed that overexpression of PSCA was significantly associated with lymph node metastasis, and overexpression of HMGA2 was significantly associated with invasive depth of pancreatic cancer." (PMID 25502777, 2014). "Further, overexpression of PSCA was significantly associated with lymph node metastasis, and overexpression of HMGA2 was significantly associated with invasive depth of pancreatic cancer." (PMID 25502777, 2014). "And overexpression of PSCA was significantly associated with lymph node metastasis, and overexpression of HMGA2 was significantly associated with invasive depth of pancreatic cancer." (PMID 25502777, 2014). "To evaluate the association between HMGA2 expression and the pathological diagnosis of pancreatic carcinoma, we investigated the expression of HMGA2 gene/protein in duct cell carcinoma and non-neoplastic tissue of the pancreas." (PMID 14647145, 2003). "To test this possibility, we examined the HMGA2 expression in pancreatic cancers in the present study, and investigated whether alterations in HMGA2 are associated with the malignant phenotype of tumours in pancreatic tissue." (PMID 14647145, 2003). "In this study, we examined the HMGA2 expression level in pancreatic carcinoma, and investigated whether alterations in the HMGA2 expression level are associated with a malignant phenotype in pancreatic tissue." (PMID 14647145, 2003). "To determine whether the altered HMGA2 mRNA expression observed in pancreatic carcinoma is associated with alterations in protein expression, we analysed the expression of the HMGA2 protein by immunohistochemistry." (PMID 14647145, 2003). "In summary, our study elucidates the mechanism by which HMGA2 enhances resistance to cell death in pancreatic cancer by inhibiting ferroptosis." (PMID 38493165, 2024). "In this study, we found that HMGA2 is highly expressed in pancreatic cancer and enhances resistance to cell death induced by chemotherapy." (PMID 38493165, 2024). "Immunohistochemical staining of HMGA2 and GPX4 in 63 pancreatic cancer tissue chip samples revealed intense GPX4 staining in high HMGA2-expressing samples." (PMID 38493165, 2024). "In our study, we first demonstrated a positive correlation between HMGA2 and GPX4, where HMGA2 overexpression increased GPX4 levels in pancreatic cancer cells, reducing lipid peroxidation under the ferroptosis inducer RSL3." (PMID 38493165, 2024). "To understand the significance of HMGA2, we compared the expression of HMGA2 between pancreatic cancer and normal tissues using publicly available RNA sequence data and proteomic data." (PMID 38493165, 2024). "In this study, we demonstrated that HMGA2 promotes pancreatic cancer cell growth and exhibits antiferroptotic effects by activating the mTORC1 pathway and enhancing GPX4 translation." (PMID 38493165, 2024). "To further elucidate the function of HMGA2, we modulated its expression in widely used pancreatic cancer cell lines." (PMID 38493165, 2024). "In pancreatic cancer, HMGA2 is related to E-cadherin, vimentin, and N-cadherin, which are the characteristic changes associated with EMT." (PMID 38493165, 2024). "Herein, we demonstrated that HMGA2 is highly expressed in pancreatic cancer tissues, mainly distributed in epithelial cells, and represents a subtype of high epithelial–mesenchymal transition." (PMID 38493165, 2024).
pancreatic cancer (continued). "Nevertheless, in most malignant tumors, the expression of HMGA2 raises, such as breast, lung, and pancreas cancer." (PMID 37689710, 2023). "Consistent with our results, HMGA2 was reportedly involved in the RAS/MEK-induced mesenchymal state in pancreatic cancer cells." (PMID 37445942, 2023). "Here, high expression of HMGA1 and HMGA2, two important members of the HMGI/HMGY family, was significantly associated with a poor prognosis in patients with pancreatic cancer." (PMID 37370109, 2023). "They reported that HMGA2, a potential treatment target in pancreatic cancer cells, had a role in RAS-mediated EMT." (PMID 37787719, 2023). "It has been reported that OLR1 promotes pancreatic cancer metastasis via increased c-Myc expression and transcription of HMGA2." (PMID 35154316, 2022). "It is reported that ANLN participates in the HMGA2-induced increase in the tumorigenicity of pancreatic cancer cells and through controlling the EZH2/miR-218-5p/LASP1 axis, ANLN deficiency dramatically reduces pancreatic tumor cell migration and invasion." (PMID 36199577, 2022). "The OLR1 gene mainly encodes a low-density lipoprotein receptor, and it has been shown that OLR1 promotes pancreatic cancer metastasis by increasing c-Myc expression and HMGA2 transcription." (PMID 36579330, 2022). "HMGA2 knockdown with siRNA has reportedly reversed the mesenchymal phenotype and decreased proliferation of pancreatic cancer cells." (PMID 35388973, 2022). "Snail is a transcriptional repressor of E-cadherin whose levels decreased after HMGA2 silencing in pancreatic cancer cells." (PMID 33668453, 2021). "miR-590 suppressed proliferation and induced apoptosis of pancreatic cancer by targeting HMGA2 and inhibiting the phosphorylation of mTOR." (PMID 34856955, 2021). "It was found that H19 promoted pancreatic cancer cell invasion and migration by upregulation of HMGA2-mediated EMT through antagonizing let-7, demonstrating the critical role of H19/let-7/HMGA2/EMT signaling axis in pancreatic cancer progression." (PMID 34439315, 2021). "It was identified that HMGA2 is a downstream target of let-7a to modulate cell proliferation, metastasis, and chemosensitivity to gemcitabine pancreatic cancer cells." (PMID 33668453, 2021). "We also found that ZFAS1 promoted the progression of pancreatic cancer in vivo by modulating the miR-497-5p/HMGA2 axis." (PMID 34552050, 2021). "Understanding the mechanisms of the ZFAS/miR-497-5p/HMGA2 ceRNA network in PC will be helpful for identifying new biomarkers or therapeutic targets in patients with pancreatic cancer." (PMID 34552050, 2021). "Analyses of the HMGA2 expression in normal pancreatic tissue and pancreatic cancer revealed clearly elevated levels in the latter with significant association with malignancy." (PMID 34302528, 2021). "ZFAS1 promoted the growth and metastasis of pancreatic cancer cells, and miR-497-5p acted as a tumour suppressor gene in pancreatic cancer by targeting HMGA2." (PMID 34552050, 2021). "HMGA2 overexpression also promoted proliferation of pancreatic cancer cells, while HMGA2 knockout significantly inhibited their colony formation ability." (PMID 32228703, 2020). "HMGA2 also hindered attenuation of pATM and γH2A.X and reduction of DNA damage in irradiated pancreatic cancer cells." (PMID 32228703, 2020). "HMGA2 expression was significantly upregulated in pancreatic cancer tissues compared with the normal pancreas tissues." (PMID 32228703, 2020). "HMGA2 and miR-194-5p were also revealed to be reversely correlated in pancreatic cancers by TCGA database analysis." (PMID 32228703, 2020). "A high expression of HMGA2 has been observed in pancreatic carcinomas, non-small cell lung carcinomas, and squamous carcinomas of the oral cavity." (PMID 32489328, 2020).
pancreatic cancer (continued). "In this context, it is noteworthy that our data correlates with a recent extensive in vivo study that implicates HMGA2 expression as a prognostic factor to poor clinical outcomes in human pancreatic cancer patients treated with DNA synthesis inhibitors." (PMID 31067275, 2019). "According to Haselmann V and colleagues, TRAIL‐R2 promotes proliferation of pancreatic cancer cell lines via inhibiting let‐7/HMGA2 pathway." (PMID 29659195, 2018). "Recently, we uncovered Hmga2 as a marker of a transient subpopulation of pancreatic cancer cells with increased metastatic ability in KP172CT mice." (PMID 30228296, 2018). "Collectively, these data suggest that Hmga2 inactivation has limited, if any, effect on overall pancreatic tumour growth." (PMID 30228296, 2018). "Hmga2 remains a prognostic marker which identifies an advanced cancer cell state in primary pancreatic tumours and marks a metastasis-driving subpopulation of cancer cells." (PMID 30228296, 2018). "Taken together, we provide evidence that Hmga2 is functionally dispensable for the malignant transformation, progression, and metastatic ability of pancreatic cancer in vivo." (PMID 30228296, 2018). "Further, we showed that overexpression of miR-93 or knocking down of HMGA2 both can decrease the invasive ability of pancreatic cancer." (PMID 29245924, 2017). "HMGA2 expression was high in low differentiated pancreatic cancer and seldom in normal and high differentiated pancreatic cancer, suggesting an important role in tumor progression." (PMID 29245924, 2017). "RUNX1 directly regulated miR-93 through suppressing expression and function of miR-93, miR-93 functions as a suppress gene in pancreatic cancer and regulates its target such as HMGA2." (PMID 29245924, 2017). "H19 can promote pancreatic cancer metastasis by derepressing let-7’s suppression on its target HMGA2-mediated EMT." (PMID 28511643, 2017). "Specific knockdown of HMGA2 inhibited cell proliferation, leading to an epithelial-mesenchymal transition in human pancreatic cancer cells." (PMID 26893968, 2016). "H19 promotes pancreatic cancer metastasis by releasing let-7-mediated inhibition on the target HMGA2-mediated EMT." (PMID 27391349, 2016). "H19 also promoted pancreatic cancer cell invasion and migration at least partially by derepressing let-7's inhibition on its target gene HMGA2 which induces EMT." (PMID 27613832, 2016). "It suggested that H19 promoted pancreatic cancer metastasis by depressing let-7's suppression on its target HMGA2-mediated EMT." (PMID 27825121, 2016). "And HMGA2 maintained oncogenic RAS-induced epithelial-mesenchymal transition in human pancreatic cancer cells." (PMID 25502777, 2014). "We have previously shown that HMGA2 promotes ERK1/2 signaling in pancreatic cancer cells in 3D collagen." (PMID 23696899, 2013). "The strong correlation between HMGA2 overexpression and the histological diagnosis of carcinoma indicates that the determination of the expression level of HMGA2 can be of great value in the diagnosis of pancreatic neoplasms." (PMID 14647145, 2003). "Intense and multifocal or diffuse HMGA2 immunoreactivity was noted in all the pancreatic carcinoma examined." (PMID 14647145, 2003). "High mobility group at‐hook 2 (HMGA2) is upregulated in pancreatic cancer." (PMID 40448344, 2025). "Similarly, in pancreatic cancer, elevated collagen type I levels promote gemcitabine resistance by upregulating HMGA2, a protein involved in chromatin remodeling, cell proliferation, and DNA repair." (PMID 40076915, 2025). "In pancreatic cancer cells, study showed that HMGA2 could bind and promote cis-element modification in the promoter region of the GPX4 gene by enhancing enhancer activity through increased H3K4 methylation and H3K27 acetylation, thus promoting GPX4 expression." (PMID 41142608, 2025).
pancreatic cancer (continued). "Intriguingly, the stromal expression of the HMGA2 protein independently predicts poorer clinical outcomes in pancreatic cancer and ampullary adenocarcinoma patients, indicating that parallel chromatin remodeling processes by HMGA2 occur in both tumoral and stromal compartments of cancers." (PMID 39858465, 2025). "We confirmed significantly high expression of HMGA2 in patients with pancreatic cancer." (PMID 38493165, 2024). "Though such naturally occurring antisense RNA may modulate the expression of the sense gene, as in the case of HMGA2 in pancreatic cancer, currently, it is unknown if VLDLR-AS1 affects the function of VLDLR in the brain." (PMID 38338752, 2024). "Furthermore, we revealed a unique feature of HMGA2 expression in pancreatic cancer based on single-cell RNA sequencing data obtained from the publicly available GSE155698 dataset." (PMID 38493165, 2024). "Of the 57 pancreatic cancers, 18 (31.6%) showed positive HMGA2 expression." (PMID 37787719, 2023). "Our findings demonstrated that HMGA2 may be involved in the development of pancreatic cancer cells and confirmed the role of EMT in periampullary carcinomas." (PMID 37787719, 2023). "Importantly, HMGA2 is re-expressed in a variety of benign and malignant tumors including breast, lung, ovarian, colorectal, and pancreatic cancers." (PMID 33668453, 2021). "The expression of ZFAS1, miR-497-5p and HMGA2 in pancreatic cancer tissues was detected by qRT-PCR." (PMID 34552050, 2021). "The expression of HMGA2 was positively correlated with E2F3 in pancreatic cancer." (PMID 32228703, 2020). "Besides, HMGA2 knockout significantly inhibited the migration and invasion of pancreatic cancer cells." (PMID 32228703, 2020). "ALDH1A1+ pancreatic cancer cells also showed enhanced HMGA2 expression." (PMID 32228703, 2020). "However, when pancreatic cancer cells were exposed to 10Gy radiation, overexpression of HMGA2 dramatically inhibited the colony formation ability of these cells, while knock-out of HMGA2 enhanced cell survival and colony formation." (PMID 32228703, 2020). "In conclusion, pancreatic cancer cell-derived exosomes could transfer the exosomal protein Lin28B to pancreatic cancer cells, thus facilitating their recruitment of PSCs via the Lin28B/let-7/HMGA2/PDGFB pathway." (PMID 31413760, 2019). "To investigate the role of Hmga2 in PDAC, we first confirmed Hmga2 expression in the carcinoma stage of pancreatic cancer tissue isolated from the well-established autochthonous KrasLSL-G12D/+;p53LSL-R172H/+;Rosa26LSL-tdTomato/+;Pdx1-Cre (KP172CT) mouse model of PDAC." (PMID 30228296, 2018). "Similarly, KPHetCT;Hmga2+/+ and KPHetCT;Hmga2CK/CK mice developed pancreatic cancer with full penetrance and comparable histology." (PMID 30228296, 2018). "HMGA2 and PSCA have been reported to be associated with pancreatic cancer." (PMID 25502777, 2014). "When the expression of the HMGA2 protein in surgical specimens of carcinomas was then analysed, multifocally or diffusely distributed intense HMGA2 immunoreactivity was noted in all the pancreatic carcinoma specimens examined." (PMID 14647145, 2003). "Thus, an increased expression level of the HMGA2 mRNA is a distinct feature of pancreatic carcinoma." (PMID 14647145, 2003). "The HMGA2 expression may assist in the histopathological differentiation of pancreatic carcinoma." (PMID 37787719, 2023). "HMGA2 upregulates IGF2BP2 expression, stabilizes m6A‐modified amyloid beta precursor‐like protein 2 (APLP2) mRNA, and promotes pancreatic cancer." (PMID 40448344, 2025). "We next knocked down c-Myc in pancreatic cancer cells, which blocked the GAA-induced expression of HMGA1 and HMGA2." (PMID 37370109, 2023). "Altogether, these and other data disclosed the role of HMGA2 as a key regulator of EMT and one of the major players in establishing a malignant phenotype in different tumors of epithelial origin, including pancreatic cancer." (PMID 34302528, 2021).
pancreatic cancer (continued). "HMGA2 was described to be responsible in conjunction with the oncogenic RAS signaling pathway for cell growth and EMT in human pancreatic cancer cells." (PMID 34302528, 2021). "Previous investigations identified HMGA2 and E2F3 as two of the eight key regulator hubs of pancreatic cancer." (PMID 32228703, 2020). "Thus, Hmga2-deficiency does not affect the histological phenotype of mouse pancreatic cancer." (PMID 30228296, 2018). "Active Src is complexed with and phosphorylates p300 in the nucleus, and the complex is bound to HMGA2 and SMYD3 genes, thereby regulating their expression to promote pancreatic tumor cell migration and invasiveness." (PMID 26695438, 2016). "HMGA2 plays particularly important role in EMT maintenance of metastatic human lung and pancreatic cancer." (PMID 26157476, 2015). "The results showed that overexpression of HMGA2 and PSCA was detected in 76.7% and 65.0% of pancreatic cancer patients, respectively." (PMID 25502777, 2014). "Our study revealed that gains of HMGA2 and PSCA were detected in one and four pancreatic carcinomas, respectively." (PMID 25502777, 2014). "In pancreatic cancer cells, this protein maintains Epithelial Mesenchymal Transition (EMT) Let-7b negatively regulates HMGA2 and, by repressing this oncogenic target, acts as growth suppressor." (PMID 20302635, 2010). "We previously demonstrated that human pancreatic carcinoma expresses high HMGA1 levels, indicating that both HMGA2 and HMGA1 are overexpressed in this lesion." (PMID 14647145, 2003). "Furthermore, c-Myc overexpression in pancreatic cancer cells with GATM knockdown restored HMGA1 and HMGA2 expression." (PMID 37370109, 2023). "The role of HMGA2 in EMT and metastatic spread has not yet been fully understood in pancreatic cancer, although, repeatedly studies have shown that overexpression of HMGA2 is accompanied by a more mesenchymal phenotype in several cancer cells." (PMID 34302528, 2021). "Furthermore, the texture feature of CT images facilitates predicting OS in conjunction with the expression of HMGA2 and C-MYC in pancreatic cancer." (PMID 33758611, 2021). "Collectively, these data suggest that Hmga2 is not required for dissemination and metastasis of pancreatic cancer." (PMID 30228296, 2018). "In addition, we analyzed the expression of the c-MYC, HMGA2 and KRAS mRNAs in the pancreatic cancer samples from the GSE data sets." (PMID 28947981, 2017). "For example, HMGA2 mediated the occurrence of triple-negative breast cancer by activating the NF-kB/IL-6/IL-8/STAT3 axis; HMGA2 activated the mTOR signaling pathway to inhibit ferroptosis, thereby enhancing the death resistance of pancreatic cancer and reducing chemotherapy sensitivity." (PMID 40703517, 2025). "HMGA2 is expressed in pancreatic carcinoma and H-PanIN but not in L-PanIN and benign lesions." (PMID 37787719, 2023). "The high-mobility group A2 (HMGA2) protein, a non-histone chromatin factor important for mesenchymal differentiation, is overexpressed in pancreatic carcinoma and was proposed to maintain a mesenchymal state of advanced pancreatic carcinoma cells by activating the Snail promoter." (PMID 24281218, 2010). "However, whether RUNX1 can diectly regulate the expression of HMGA2 in pancreatic cancer is still not clear, and we plan to testify this axis in the future in vivo." (PMID 29245924, 2017).